PAX1 (paired box 1)
Diseases named in the same sentence as PAX1 in open-access papers (continued):
Sharing a sentence is not in itself a finding about the gene and the disease.
tumor (22 papers, 2011 to 2025). "To test the adjunct role of DNA methylation for MRI, we calculated the combined diagnostic performances of PAX1 methylation and tumor size." (PMID 34335930, 2021). "To evaluated and compared the diagnostic performances of PAX1 methylation and tumor size in predicting the tumor partial response at T2 stage, we generated the ROC analysis curves." (PMID 34335930, 2021). "Methylation of PAX1 promoter is an important epigenetic regulation associating to the development and the metastasis of the tumor." (PMID 30636379, 2019). "PAX1 hypomethylation was found to be a risk factor for tumor residual after chemo-radiotherapy." (PMID 37533109, 2023). "PAX1 might regulate immune system, causing changes in tumor microenvironment and affecting radiosensitivity." (PMID 37533109, 2023). "In this study, PAX1 hypomethylation, tumor size, pathological type, and lymph node status were identified as independent risk factors for radiotherapy response." (PMID 37533109, 2023). "The loss of PAX1 function caused by PAX1 methylation may affect the immune function, whereas demethylation caused by radiotherapy reactivates the normal regulatory function of PAX1 on the immune system, causing changes in tumor microenvironment and affecting radiosensitivity." (PMID 37533109, 2023). "The AUCs of PAX1 methylation and tumor size for predicting PR at T2 were 0.84 (P<0.05, 95% CI:0.73-0.95) and 0.80 (P<0.05, 95% CI: 0.69-0.91)." (PMID 34335930, 2021). "Taken in aggregate, PAX1 methylation level is a better indicator of the early molecular changes in the tumor during treatment than MRI parameters to timely detect patients who are not sensitive to radiotherapy and adjust treatment regimen." (PMID 34335930, 2021). "The gradual decrease in PAX1 methylation level was consistent with the change in tumor size in radiotherapy." (PMID 34335930, 2021). "In present study, PAX1 methylation level showed slightly better performance than tumor size for distinguishing between CR or residual tumor cells (AUC 0.84 vs 0.80)." (PMID 34335930, 2021). "Gene ontology analysis also revealed that PAX1 reduced the genes for cell-cycle and mitosis pathways, further indicative of it tumor suppressor role." (PMID 31235851, 2019). "Another study reported PAX1 expression‐inducing tumor formation following subcutaneous injection of cultured cells expressing PAX1 into nude mice." (PMID 30636379, 2019). "For this purpose, four tumour-suppressor genes: Ras Association Domain Family Member 1 (RASSF1), Paired Box 1 (PAX1), Cadherin 1 (CDH1) and Phosphatase and Tensin Homolog (PTEN) were analysed." (PMID 31450846, 2019). "Herein, we focused on the epigenetic impact on OC formation by analysing the methylation levels of the RASSF1, PTEN, CDH1 and PAX1 tumour suppressor genes’ regulatory sequences." (PMID 31450846, 2019). "The present study demonstrated that PAX1 plays a tumor suppressor role in response to the onset of oncogenic stress, including growth factor stimulation." (PMID 31235851, 2019). "The frequency of PAX1 methylation was 80.7% (151/187) in the tumor samples, which is significantly higher than that (25%, 4/16) in the paracancerous samples." (PMID 28241446, 2017). "The frequency of PAX1 methylation was 100% (14/14) in the tumor tissues, which is significantly higher than that (21.4%, 3/14) in the paracancerous tissues." (PMID 28241446, 2017). "In addition, at the △Cp threshold of 6.38, PAX1 methylation distinguished CR and PR with the high specificity of 0.88 compared to only 0.60 for tumor size." (PMID 34335930, 2021). "In 68 patients with high PAX1 methylation level, we analyzed the change of tumor size (n=68) and during radiotherapy to explore the correlations between therapeutic response and the change rate of tumor size during CCRT." (PMID 34335930, 2021).
tumor (continued). "Additionally, other studies showed that methylation of CpG islands in the PAX1 promoter region regulates cervical neoplasia, resulting in their characterization of PAX1 as a tumor suppressor gene." (PMID 30636379, 2019). "Together, these results support our hypothesis that PAX1 is a tumor suppressor that is responsive to environmental factors, such as EGF, and inhibits EGF-induced EMT and malignant phenotypes." (PMID 31235851, 2019). "Moreover, detection of PAX1 methylation displayed relatively good sensitivity and specificity for the diagnosis of these tumors and holds great promise for tumor screening or as a prognostic marker." (PMID 30636379, 2019). "Moreover, PAX1 significantly inhibited tumor growth in cells pretreated with EGF." (PMID 31235851, 2019). "HR-HPV infection appears to increase DNMT expression, thereby promoting cervical carcinogenesis through aberrant methylation and subsequent silencing of tumor-suppressor genes such as PTEN, PAX1, and TSLC1." (PMID 41226543, 2025). "DNA methylation of PAX1 and ZNF582 genes in both tumor and paracancerous tissues was detected successfully using the current analysis." (PMID 28241446, 2017). "The methylation rates of PAX1 and ZNF582 in ESCC tumor and paracancerous tissues were 100% and 21.4% (p = 0.006), 85.7% and 0% (p < 0.001), respectively." (PMID 28241446, 2017). "The DNA methylation levels and frequencies of PAX1 and ZNF582 genes were markedly higher in ESCC tumor tissues compared to those in paracancerous tissues." (PMID 28241446, 2017). "MeDIP-qPCR and qPCR were performed to measure demethylation status and mRNA re-expression level of 7 tumor-suppressor genes (CCNA1, CHFR, FHIT, PAX1, PTEN, SFRP4, TSLC1) in Hela and Siha cells after silencing DNMT1." (PMID 21999220, 2011). "In CAC patients with small tumor size (<4 cm), PAX1m-positive patients showed a longer 5-year PFS, suggesting that PAX1 gene methylation might be useful for monitoring the 5-year progression in CAC patients with small tumor size." (PMID 33376722, 2020). "The median methylation levels (beta-values) of the non-tumor specimens and tumors were 0.05 and 0.58, respectively, while PAX1 promoter methylation levels in non-tumor tissues were significantly lower than those in tumors (Mann-Whitney U test, p < 0.0001)." (PMID 31235851, 2019). "Using quantitative methylation-specific PCR (qMSP), we demonstrated for the first time that PAX1 and ZNF582 genes were aberrantly methylated in ESCC tumor tissues compared to the paracancerous normal tissues, and the levels of DNA methylation were significantly associated with tumor progression." (PMID 28241446, 2017). "Paired boxed gene 1 (PAX1) and zinc finger protein 582 (ZNF582) are two tumor suppressor genes." (PMID 28241446, 2017). "The methylation levels of both PAX1 and ZNF582 genes were significantly higher in tumor tissues compared to non-tumor paracancerous tissues." (PMID 28241446, 2017). "Our current study demonstrated for the first time that both the levels and frequencies of PAX1 and ZNF582 methylation were greatly higher in the ESCC tumor tissues compared to non-tumor paracancerous tissues." (PMID 28241446, 2017). "PAX1 and ZNF582 methylation testing has an excellent accuracy, sensitivity and specificity in distinguishing ESCC tumor tissues from non-tumor tissues." (PMID 28241446, 2017).
infection (7 papers, 2014 to 2024). The state of being infected such as from the introduction of a foreign agent such as serum, vaccine, antigenic substance or organism. "Together with the present study, the infection of HPV may cause the promoter methylation of PAX1 and result in the reduction of phosphatases’ expression." (PMID 31235851, 2019). "JAM3 and PAX1 methylation have statistical significance with HPV sustained infection lasting more than 3 years compared to less than 3 years." (PMID 38611108, 2024). "In this study, PAX1 methylation was clinically relevant to the HPV16/18 infection, with higher levels of PAX1 methylation in HPV16/18-positive patients than in HPV16/18-negative patients." (PMID 37533109, 2023). "The level of Pax1 was decreased to 21% or 3% of that in the control by infection with shPax1-a or shkPax1-b lentivirus, respectively." (PMID 30872687, 2019). "PAX1 methylation level could serve as a valuable tool in guiding individualized clinical decisions regarding ECC for patients with HPV 16/18 infection, particularly in cases of low-grade cytological findings." (PMID 38849868, 2024). "Taking methylated JAM3 and PAX1 as another biomarker of sustained infection is a new finding in this study, suggesting that this group of women may progress more rapidly to precancerous lesions, which is worthy of clinical study." (PMID 38611108, 2024). "This suggests that the three LIM domains of Pax1 may have redundant or overlapping functions in infection-related morphogenesis." (PMID 24505448, 2014).
adenocarcinoma (3 papers, 2024 to 2026). A common cancer characterized by the presence of malignant glandular cells. "Specifically, these two cases exhibited notably high levels of PAX1 and JAM3 methylation (Patient 1: ΔCtPAX1 = 2.52, ΔCtJAM3 = 5.28, LBC: NILM; Patient 2: ΔCtPAX1 = 1.82, ΔCtJAM3 = 3.72, LBC: adenocarcinoma)." (PMID 39659794, 2024). "Notably, two cases of adenocarcinoma in this study, which were negative for hrHPV and had normal cytological results, exhibited high methylation levels of both PAX1 and JAM3." (PMID 41239544, 2026).
PAX1 also shares sentences with these, for which no sentence is quoted: carcinoma in situ (2 papers); head and neck squamous cell carcinoma (2); idiopathic scoliosis (2); age-related macular degeneration (1); anemia (1); aniridia (1); benign ovarian tumors (1); cervical adenocarcinoma (1); CHARGE syndrome (1); congenital heart defects (1); developmental delay (1); dysplasia (1); ectodermal dysplasia (1); endometrial carcinoma (1); Ewing sarcoma (1); gastric cancer (1); hyperplasia (1); hypoparathyroidism (1); Kyphoscoliosis (1); lymphopenia (1); male pattern baldness (1); maturity-onset diabetes (1); melanoma (1); microtia (1); Oligodontia (1); oral lichen planus (1); ovarian tumors (1); pneumonia (1); rectal cancer (1); renal coloboma syndrome (1).
A further 7 diseases each share a sentence with PAX1 in 1 paper.